VCAM1 (vascular cell adhesion molecule 1)
Diseases named in the same sentence as VCAM1 in open-access papers (continued):
Sharing a sentence is not in itself a finding about the gene and the disease.
COVID-19 (78 papers, 2020 to 2025). A disease caused by infection with severe acute respiratory syndrome coronavirus 2. "This hyperinflammatory state was accompanied by coagulative disturbances, including elevated D-Dimer, E-sel, ICAM-1, and VCAM-1, aligning with previous studies highlighting COVID-19-associated coagulopathy as a key factor contributing to LC sequelae." (PMID 41226453, 2025). "We found an inverse association between genetically predicted macrophage colony stimulating factor (MCSF), soluble intercellular adhesion molecule-1 (sICAM), and soluble vascular cell adhesion molecule-1 with risk of COVID-19 outcomes." (PMID 39319267, 2024). "In the group of patients with DM, increased VCAM-1 levels at ICU admission remained associated with death due to COVID-19 in the multivariate model (HR: 1 [1-1.001], P<0.006)." (PMID 37585916, 2023). "Endothelial activation, characterized by elevated serum levels of VCAM-1, was associated with death in patients with severe COVID-19 and comorbid DM." (PMID 37585916, 2023). "Endothelial cell adhesion molecules such as ICAM-1 and VCAM-1, which were also used as endothelial damage markers, were elevated in COVID-19 and associated with disease severity in previous reports." (PMID 35784283, 2022). "In the present study, we showed that ICAM-1 and VCAM-1 were elevated more in COVID-19 patients than in controls and were associated with resistin levels." (PMID 35784283, 2022). "Elevated concentrations of C5a, Galectin-3, ICAM-1 and VCAM-1 on presentation were associated with the composite outcome of ICU- admission or 30-day mortality in COVID-19 and controls, yet more pronounced in COVID-19." (PMID 36203596, 2022). "Serum soluble ST2, VCAM-1, and hs-TnI were evaluated upon admission in 280 consecutive patients hospitalized with COVID-19-associated pneumonia in a single, tertiary care center." (PMID 35836945, 2022). "The studies confirm the role of adhesion molecules in COVID-19 complications, indicating that high circulating levels of VCAM-1 and E-selectin are associated with increased COVID-19 severity, as a meta-analysis from 2021 showed." (PMID 35888103, 2022). "VCAM-1 has also been reported to be elevated in the blood plasma of COVID-19 patients and was found to be associated with acute vascular inflammation." (PMID 34307198, 2021). "In summary, we identified an elevated vulnerability of those with a history of stroke to severe COVID-19 underlying inflammatory responses (i.e., VCAM-1) and procoagulant pathways, suggesting monotonic relationships, thus implicating causality." (PMID 33732102, 2021). "We also found EC dysfunction in an autopsied lung collected from a patient who died of severe COVID-19 as evidenced by VCAM1 staining, which is associated with extensive edema, and viral infection evidenced by extensive viral staining in the lung." (PMID 34335981, 2021). "Vascular dysfunction with endothelial cell activation is linked to lethal COVID-19, and highly elevated soluble VCAM-1 and ACE2 at admission to ICU may predict unfavorable outcomes." (PMID 38276214, 2024). "Using those cut-off values in the Kaplan–Meier analysis, COVID-19 patients with highly elevated VCAM-1 levels had a significantly higher risk of 30-day mortality compared to those with lower values (with a death ratio of 68% vs. 37%, respectively, Log rank p = 0.0031)." (PMID 38276214, 2024). "Moreover, in a meta-analysis (n = 2,213), VCAM-1 levels were linked with increased disease severity in COVID-19 patients." (PMID 35836945, 2022). "Thus, correlations were performed in the current investigation, implying that plasma levels of CRP, SAA, IL-6, CXCL10, VCAM-1, and IL-10, among the linked, exhibit a significant and beneficial association with COVID-19 patient progression." (PMID 35958594, 2022). "In further trials, VCAM-1 was associated with COVID-19-related mortality." (PMID 35836945, 2022).
COVID-19 (continued). "We adopted the network medicine-based approaches to investigate the stroke-associated genes, especially VCAM-1, involved in the comorbidities between stroke and COVID-19 and preliminarily inspect the underlying inflammatory endophenotypes between COVID-19 and stroke." (PMID 33732102, 2021). "Higher circulating levels of soluble VCAM-1 and E-selectin have been reported in patients with COVID-19, and are associated with elevated levels of pro-inflammatory cytokines and chemokines such as tumor necrosis factor-α (TNF-α), indicating endothelial injury." (PMID 34835015, 2021). "At three months post infection, high levels of D-Dimer, E-Sel, ICAM-1, and VCAM-1 were observed, according to a previous study reporting that, at 3 months after COVID-19, D-Dimer level was increased in 15% of the subjects who had recovered from COVID-19." (PMID 41226453, 2025). "To further characterize the impact of COVID-19 on endothelial function, we examined the expression of vascular cell adhesion molecule-1 (VCAM-1), a crucial marker of endothelial activation that mediates the adhesion of leukocytes to vascular wall." (PMID 40109358, 2025). "Immunohistochemical staining of lung tissue from COVID-19 patients revealed an increase in VCAM-1 expression in small vessels compared to healthy donors." (PMID 40109358, 2025). "Regarding critical COVID-19 group, prior treatment with RAAS inhibitors was also associated to significantly higher s-VCAM-1 values on days 3–4 and days 5–8." (PMID 39862311, 2025). "The levels of the coagulation markers intercellular adhesion molecule-1 (ICAM-1) and E-selectin were consistently upregulated in post-COVID-19 female patients, in contrast to those of vascular cell adhesion molecule-1 (VCAM-1), P-selectin, and chemokine IL-8." (PMID 37896963, 2023). "Higher levels of VCAM-1 in patients with DM was better at predicting death of patients with severe COVID-19 and comorbid DM, and their cut-off values were useful for stratifying patients with a worse prognosis." (PMID 37585916, 2023). "Inversely to P-selectin and IFN-γ, vaccination was in positive correlation with E-selectin, ICAM-1, and VCAM-1 in post-COVID-19 male patients." (PMID 37896963, 2023). "Serum Levels of VCAM-1 is significantly increased in endothelial cell of COVID-19 affected patients with mild symptom, dramatically increase in severe case and also displayed a massive reduction after antiviral treatment." (PMID 36949176, 2023). "LDH was negatively correlated with E-selectin (r = −0.875, p = 0.001) and VCAM-1 (r = −0.731, p = 0.030) expression in post-COVID-19 female patients." (PMID 37896963, 2023). "The adhesion molecules P-selectin and VCAM-1 were more upregulated in male patients, while the IL-6 levels were generally increased in our COVID-19 and/or post-COVID-19 patients." (PMID 37896963, 2023). "It has been observed that the expression of the vascular cell adhesion molecule 1 (VCAM-1) adhesion factor on epithelial cells is increased in patients with severe COVID-19." (PMID 36936055, 2023). "AST (r = 0.569, p = 0.007), ALT (r = 0.573, p = 0.008), and GGT (r = 0.589, p = 0.023) were positively correlated with VCAM-1 expression in post-COVID-19 patients." (PMID 37896963, 2023). "Resistin was significantly associated with IL-6, IL-8, IL-10, VCAM-1 and ICAM-1 in the COVID-19 patients." (PMID 35784283, 2022). "Accordingly, we undertook a comparative analysis of novel cardiac biomarkers sST2 and VCAM-1 as well as high-sensitive Troponin I (TnI) in a 1-year follow-up of COVID-19 patients." (PMID 35836945, 2022). "Based on the pathophysiological processes involved, VCAM-1 represents a promising prognostic marker for the assessment of in-hospital mortality in COVID-19." (PMID 35836945, 2022). "ICAM-1 and VCAM-1, soluble markers of endothelial inflammatory activation, rise in severe COVID-19 cases." (PMID 36430566, 2022).
COVID-19 (continued). "Overall, C5a and VCAM-1 concentrations were elevated and E-selectin concentrations decreased in COVID-19 cases compared to controls (p<0.001 for all markers) with a borderline difference in sC5b-9 levels (p=0.037)." (PMID 36203596, 2022). "Soluble forms of ICAM-1, VCAM-1 and E-selectin are used as biomarkers for endothelial cell activation, and several studies demonstrate increased concentrations of these proteins in COVID-19 patients related to the disease severity." (PMID 36203596, 2022). "Of the widely used endothelial cell activation markers VCAM-1 (vascular cell adhesion molecule) and E-selectin, VCAM-1 was higher, whilst E-selectin was lower in COVID-19 patients as compared with the non-COVID-19 CAP groups." (PMID 35660785, 2022). "In order to add information on the regulation mechanisms between those cytokines, it would be useful to measure serum levels of IL-1 and TNF-α during the acute phase of COVID-19, testing their correlation with acute and post-acute VCAM-1 and IL-8 values." (PMID 36062000, 2022). "using serum from a large cohort of COVID-19 patients found that the surface expression of E-selectin, VCAM-1 and ICAM-1 were around 2, 4 and 3-fold increase in HUVEC compared to control serum." (PMID 35837388, 2022). "The endothelial perturbation biomarker VCAM-1 emerged as a promising prognostic tool for mortality in COVID-19." (PMID 36143072, 2022). "Given the high availability and simple use of the existing ELISA kits, the measurement of VCAM-1 can be considered in the routine laboratory panel of COVID-19 patients on admission." (PMID 36143072, 2022). "C5a and VCAM-1 concentrations were significantly elevated and E-selectin concentrations decreased in COVID-19 out- and inpatients compared to the respective controls." (PMID 36203596, 2022). "VCAM1 and VEGF, two parameters associated with endothelial activation, were significantly higher in individuals with COVID-19." (PMID 36289900, 2022). "Given the involvement of sST2 and VCAM-1 in inflammatory processes and the previous reports on their role in COVID-19, their potential impact on prognosis also in the long term seems plausible." (PMID 35836945, 2022). "A metabolomic data analysis had also confirmed the up-regulation of VCAM-1 in patient with COVID-19." (PMID 33732102, 2021). "Further research is needed to investigate the role of VCAM-1 (or the immune response driving its expression), in the pathogenesis of severe COVID-19." (PMID 34422854, 2021). "Soluble VCAM-1 was 1.49-fold higher in men as compared to women with COVID-19 (p = 0.018, cohort 1)." (PMID 34835015, 2021). "COVID-19 patients had significantly higher plasma concentrations of soluble VCAM1 (sVCAM1) (5,739 ± 3,293 vs. 3,700 ± 2,124 ng/ml; p = 0.009), but lower levels of D-dimers, vWF-A2, sICAM1, sTREM1, VEGF, and P-selectin, compared to non-COVID-19 patients." (PMID 34422854, 2021). "We analyzed the protein expression of circulating markers that reflect the endothelial activation (VCAM-1 and E-selectin) in men and women hospitalized with COVID-19." (PMID 34835015, 2021). "Evaluate the relationship between lymphopenia and serum vitamin D, FasL, VCAM-1, and apoptotic markers in hospitalized patients with COVID-19." (PMID 33621190, 2021). "We observed sex differences in circulating blood levels of the endothelial injury markers VCAM-1 and E-Selectin, which were significantly higher in men as compared to women hospitalized with COVID-19." (PMID 34835015, 2021). "The inflammatory endophenotype network between stroke and COVID-19 is composed of three subnetworks, in which the largest one is centered around the hub gene VCAM-1." (PMID 33732102, 2021). "Meanwhile, SARS-CoV-2 host genes, such as ACTB, KPNA2, and JUN, interact with SAMHD1, VCAM1, and HMOX1, in the PPI network, indicating possible mechanisms of COVID-19 associated stroke." (PMID 33732102, 2021).
COVID-19 (continued). "Circulating endothelial injury markers VCAM-1 and E-selectin were measured in men and women diagnosed with COVID-19." (PMID 34835015, 2021). "Serum VCAM1 levels were also significantly elevated in severe COVID-19 patients compared to mild patients and controls, and significantly decreased in the convalescence phase compared to severe patients." (PMID 34108016, 2021). "Analysis from patients hospitalized with COVID-19 showed concordant higher circulating VCAM-1 and E-Selectin levels in men, compared to women." (PMID 34835015, 2021). "Our results corroborate this hypothesis since hypertensive COVID-19 patients presented significantly higher s-Endocan and/or s-VCAM-1 concentrations than normotensives among severe and critical COVID-19 groups throughout the first week of hospitalization." (PMID 39862311, 2025). "However, all COVID-19 patient groups had significantly higher values of s-VCAM-1 compared to controls (P < 0.001)." (PMID 39862311, 2025). "Interestingly, VCAM-1 expression was also detected in large vessels in both healthy and COVID-19 lung tissue." (PMID 40109358, 2025). "In parallel, adhesion molecules, early markers of endothelial activation/dysfunction, such as selectins (E-, P-, and L-selectin), soluble intercellular adhesion molecule 1 (ICAM-1), and vascular adhesion molecule 1 (VCAM-1), are also elevated in plasma samples from COVID-19 patients." (PMID 38494528, 2024). "VCAM-1 was upregulated in the post-COVID-19 male patients compared to the female ones (p < 0.01)." (PMID 37896963, 2023). "Similarly, circulating levels of endothelial markers such as ICAM-1, VCAM-1, and prothrombotic markers such as vWF or P-selectin have been reported in this cohort of COVID-19 ARDS patients." (PMID 37283766, 2023). "Moreover, increasing serum VCAM-1 levels in COVID-19 patients during hospitalization correlated with increased risk of ICU admission and mortality." (PMID 36941580, 2023). "Another study showed that in the serum of COVID-19 patients (n = 250) VCAM-1 and ICAM-1 levels positively correlated with SARS-CoV-2 RNAemia." (PMID 36941580, 2023). "Furthermore, the presented study revealed increased and sustained VCAM-1 plasma levels in post-COVID-19 male patients." (PMID 37896963, 2023). "Indeed, while concentrations of C5a and VCAM-1 were higher and E-selectin concentrations lower in COVID-19 cases vs. the respective controls, the relative difference when comparing inpatients vs. outpatients was comparable in cases and controls." (PMID 36203596, 2022). "At first sight, the association of elevated C5a, ICAM-1 and VCAM-1 concentration on admission with ICU admission or 30-day mortality did not point towards a specific feature of COVID-19, as it was observed in cases and controls in the present study." (PMID 36203596, 2022). "The elevated levels of vascular endothelial activation markers, including von Willebrand factor (VWF), plasminogen activator inhibitor, intercellular adhesion molecule-1 (ICAM-1), and vascular cell adhesion molecule-1 (VCAM-1), have been observed in patients with COVID-19." (PMID 36551272, 2022). "Indeed, serum VCAM1 concentration, as well as that of the other endothelium-derived molecule studied, VEGF, has been linked with disease severity in COVID-19 patients and this was also detected in our study." (PMID 36289900, 2022). "Another suggested mechanism of disease for COVID-19 is the loss of the endothelial integrity associated with changes in the surface expression of intracellular adhesion molecule-1 (ICAM1), vascular cell adhesion protein-1 (VCAM1) and the tight junction scaffold protein zonula occludens-1 (ZO-1)." (PMID 35050236, 2022). "Positive aPL sera from COVID-19 patients induced upregulation of the cell adhesion molecules E-selectin, vascular cell adhesion molecule 1 (VCAM-1), and intracellular adhesion molecule 1 (ICAM-1) in HUVECs, which was abolished by total IgG depletion from the COVID-19 sera." (PMID 34977191, 2021).
COVID-19 (continued). "Further validation in human samples from patients hospitalized with COVID-19 infection showed that circulating endothelial injury markers VCAM-1 and E-Selectin were concordantly impacted with higher expression in men diagnosed with COVID-19, as compared to women." (PMID 34835015, 2021). "Hence, the aim of our study was to evaluate and compare the profiles of endocan and other endothelial dysfunction biomarkers (ICAM-1, VCAM-1 and E-selectin) in hospitalized patients with different stages of COVID-19 severity, including critical COVID-19 on VV-ECMO patients." (PMID 39862311, 2025). "Thus, VCAM-1 might represent a promising parameter reflecting short term effects in COVID-19, while long-term prognostic impact is limited." (PMID 35836945, 2022). "Finally, VCAM-1 emerged as a promising prognostic biomarker for mortality in COVID-19." (PMID 36143072, 2022). "Since circulating levels of these isoforms reflect enhanced expression of the respective adhesion molecules, we postulate that overexpression of VCAM1 in COVID-19 patients could participate in massive recruitment of immune cells in the lung, contributing to lung injury and prolonged MV." (PMID 34422854, 2021). "However, as a vasculitis disorder, the role of VCAM-1 in the pathogenesis of COVID-19 remains unknown." (PMID 33621190, 2021). "Accordingly, anti-VCAM1 humanized monoclonal antibody could represent a promising therapeutic strategy, in order to dampen coagulopathy and improve outcomes in severe forms of COVID-19." (PMID 34422854, 2021). "Notably, VCAM1 also plays an important role in COVID-19-induced vasculitis." (PMID 34108016, 2021). "A previous study reported that lymphopenia in SARS may be due to enhanced vascular sequestration associated with increased soluble vascular cell adhesion molecule-1 levels, but the mechanism is not clear in patients with COVID-19." (PMID 33206680, 2020). "Vascular cell adhesion molecule-1 (VCAM-1) and ICAM-1 levels were found to be elevated in the blood of patients with mild COVID-19 and dramatically elevated in severe cases, decreasing during the convalescence phase." (PMID 41583455, 2025). "Taken together, serum VCAM-1 and ACE2 at ICU admission had a capacity to predict mortality in COVID-19." (PMID 38276214, 2024). "After 6 months of infection, PLWH exhibited significantly higher serum levels of ACE2, VCAM-1, and ICAM-1 (P < 0.01, respectively) compared to PNLWH with COVID-19." (PMID 39669584, 2024). "Among these parameters, VCAM-1 and ACE2 showed significantly higher serum levels in COVID-19 patients with early death vs. convalescent subjects." (PMID 38276214, 2024). "Patients with COVID-19-induced ARDS have higher serum levels of endothelial damage markers such as angiopoietin-2, intercellular adhesion molecule-1, vascular cell adhesion molecule-1, P-selectin, and E-selectin than patients with other types of ARDS." (PMID 39408067, 2024). "First reports have shown that serum VCAM-1 and ICAM-1 levels were increased in COVID-19 patients (n = 36), as compared to healthy subjects (n = 16), positively correlating with disease severity and tending to decrease during convalescence." (PMID 36941580, 2023). "In contrast, a study of lung tissue from patients who died from COVID-19 (n = 9) showed a reduced local expression of ICAM-1, VCAM-1, E-selectin, and P-selectin." (PMID 36941580, 2023). "Patients with severe COVID-19 are known to have increased vascular inflammation characterized by increased expression of lung endothelial ICAM-1 and VCAM-1, which facilitate the infiltration of inflammatory cells into the lung tissue." (PMID 38143504, 2023). "In the present cohort of COVID-19 patients, thrombomodulin, IL-6, FVIII, VWF:Ag, sEPCR, sC5b9, tPA, PAI-1 activity, C4, ICAM-1 and VCAM-1 plasma levels were higher than normal ranges, in line with previous studies that included patients with a severe disease." (PMID 36143072, 2022).